TNF (tumor necrosis factor)
Diseases named in the same sentence as TNF in open-access papers (continued):
Sharing a sentence is not in itself a finding about the gene and the disease.
infection (continued). "EcoHIV-infection induced a prominent change in various neuroinflammatory markers (i.e., IL-1β, IL-6, TNF-α, and NF-κB) in the brain relative to the control animals." (PMID 34067600, 2021). "Retrospective analysis of human samples after an Italian CHIKV outbreak revealed an increase in IL-6 during the acute phase of infection, and low levels of IL-1β, TNF-α, IL-12, IL-10, IFN-γ, and IL-5 that increased as disease progressed to the chronic state." (PMID 34106915, 2021). "Of the seven inflammatory mediators that increased in the late stage of infection in the mice that received vehicle, three—TNF-α, IL-6, and IP-10—were significantly in both the early and late phases." (PMID 34835277, 2021). "The role of rs361525 of TNF-α gene located on the short arm of chromosome 6 in the course of infection with 2009 H1N1 influenza virus was confirmed." (PMID 33766078, 2021). "On the contrary, the importance of TNF-α production in response to infection has been demonstrated by multiple research groups." (PMID 35003518, 2021). "Recently, palmitoleate was also shown to inhibit TNFα, IL-1β and IL-6 proinflammatory cytokine responses in candida-infection stimulation analysis." (PMID 33886600, 2021). "Treatment with the broadly immunosuppressive dexamethasone leads to a similar time to death, indicating that TNFα is a critical factor in establishing control of Coccidioides in our infection model." (PMID 35174101, 2021). "Serum proinflammatory cytokines (interleukin-6 [IL-6], IL-1β, gamma interferon, and tumor necrosis factor alpha) and the anti-inflammatory cytokine IL-10 were first detected at 12 h postburn with infection and continued to increase until death." (PMID 34152806, 2021). "Basic measures include pain and infection control, adequate local wound care, systemic therapy (e.g., corticosteroids), and targeted therapy (e.g., anti-TNF agents or anti-interleukin-12 and 23)." (PMID 33995526, 2021). "While elevated levels of Fractalkine, ITAC, IL-7, IL-8, and TNFα are observed for both countries in their respective pre-infection groups, they differ in that they exhibit additional biomarkers unique to each country." (PMID 33731158, 2021). "At 4 hr post-infection, we detected increased Mincle expression (red) in WT cells receiving TNFα or O. tsutsugamushi (5 MOI) alone, with more intense staining observed in cells receiving TNFα 30 min prior to infection." (PMID 34320039, 2021). "This similar time to death, even with the termination of anti-TNFα treatment, indicates that failure to develop a proper immune response to the initial infection has long-reaching consequences." (PMID 35174101, 2021). "In Rwanda, Fractalkine, GMCSF, ITAC, IL-1ß, IL-6, IL-7, IL-8, MIP-1α, and TNFα concentrations were significantly increased in the pre-infection group compared to the uninfected group." (PMID 33731158, 2021). "During chronic neuroinflammation or infection, CNS levels of lipopolysaccharide (LPS) and LPS-induced tumor necrosis factor-α (TNFα) are increased." (PMID 34285658, 2021). "A defective CD8+pSTAT1 and pSTAT3 pathway, expanding senescent CD57+KLG1+ T cell repertoire and the increasing TNF-α and IL-6 levels with infection duration, reduces cytokine responsiveness of vaccine-induced T-cells." (PMID 33746974, 2021). "On the contrary, the low dose infected macaques demonstrated an early TNF-α response in the Mtb-specific CD4+ T cells at weeks 1 which decreased at week 3 post-infection." (PMID 34484203, 2021). "As expected, the pathways that interacted with TNF were the most, mainly cellular response to interferon-gamma-related anti-infection pathways." (PMID 34311758, 2021). "This proves that the designed circuit promotes the levels of TNFα in micro-environment establishing anti-leishmanial response during the early stage of the infection." (PMID 35011356, 2021).
infection (continued). "In Zambia, Fractalkine, ITAC, IL-7, IL-8, IL-23, and TNFα concentrations were significantly increased in the pre-infection group compared to the uninfected group in univariate comparisons." (PMID 33731158, 2021). "TNF-α is regarded as a critical pro-inflammatory cytokine and immunomodulatory molecule that occurs in the acute phases of inflammation and infection." (PMID 34945535, 2021). "Previous results indicate that infection by C. gattii induces the production of cytokines related to the Th1 profile more than other species of Cryptococcus, such as IL-1β, TNF-α and IL-6." (PMID 34526536, 2021). "As expected, GL or GM pretreatments effectively (P < 0.05) decreased the increased pro-inflammatory cytokines (IFN-γ, TNF-α, and IL-6) induced by ST infection, whereas, they increased anti-inflammatory cytokine IL-10 secretion (P < 0.05)." (PMID 34239908, 2021). "During infection, activated macrophages secrete proinflammatory cytokines (e.g., TNF-α, IL-1β and IL-6) and inflammatory mediators (e.g., NO and PGE2) to regulate inflammatory responses against pathogens." (PMID 34564598, 2021). "Although not statistically significant, we observed that the early appearance of several pro-inflammatory cytokines and chemokines (TNFα, MCP-1, IL15, and G-CSF) were more associated with ZIKV-Brazil and/or ZIKV-FP infections." (PMID 34120576, 2021). "With the introduction of the designed synthetic circuit in infected cells, there is rapid increase of TNFα which has been observed with nearly 10 fold change (60 min post infection) and which further increases with Miltefosine treatment." (PMID 35011356, 2021). "Recruited NK cells, in proximity to recruited Ly6Chi monocytes, produce interferon−γ (IFN-γ) and thus drive monocyte differentiation into TNF- and iNOS-producing DCs at the site of infection." (PMID 34367182, 2021). "Upregulation of MHCI, TNFα and IL-1 are mediators of the innate immune response, orchestrating the innate cell to respond to the infection, and activating the protective adaptive immune response." (PMID 34835184, 2021). "Infection of the BMDMs with MRSA robustly upregulated the secretion of an array of inflammatory mediators that included TNF-α, IL-12, IFN-γ, and IL-10." (PMID 34681611, 2021). "Expression of CRP is induced by IL-6 and other cytokines (IL-1β, TNF) via NF-κB and other transcription factors as part of the acute-phase response or during inflammatory conditions and infections." (PMID 34925360, 2021). "A second cohort of mice was followed for survival and disease progression up to 105 days post infection (42 days after starting anti-TNFα antibody treatment)." (PMID 35174101, 2021). "TNF-α is a common inflammatory factor, and under physiological conditions, its concentration is very low but increases dramatically during the onset of infection." (PMID 34495248, 2021). "There was an interaction (p < 0.05) between probiotics and infection on mitogen-induced TNFα secretion from CLN cells, with BBE supplementation significantly reducing TNFα production in uninfected pigs, but not in infected animals." (PMID 35069576, 2021). "We also observed a significant increase in the levels of TNF-α in the lung lysates of M. tb-infected mice treated with DEM at 8 weeks post-infection compared to the sham group." (PMID 35371562, 2021). "Neutrophils are also produced early in response to infection, and neutrophil chemotaxis in humans is usually mediated by factors such as IL-8, IL-1, TNF-α, and complement C5a." (PMID 34603560, 2021). "In the mono-infection model, the levels of TNF-α were significantly higher in TRPV4 KO mice than those of wild type and TRPV1 KO mice (p < 0.05 and p < 0.001, respectively)." (PMID 34804016, 2021). "The exosomes secreted by microglia during TMEV infection also induced the expression of pro-inflammatory cytokines, IL-6, IL-12, and TNFα, and chemokines, CCL2, in bystander uninfected microglia." (PMID 34485270, 2021).
infection (continued). "The death rates of individual cells depend on their infection status, their exposure to TNF, and are directly interpolated from measured values." (PMID 34016976, 2021). "The mRNA levels of interleukin 1β (IL1β) and tumor necrosis factor alpha (TNFα) in the liver of WT-infected mice were significantly higher than those in the liver of ΔspvB-infected mice at 3 days post-infection." (PMID 33475464, 2021). "The increasing presence of activated immune cells during the early phase of infection, especially on day 3 p.i., further resulted in an abundant IL-1β and TNF-α expression in the spleen, similar to that measured in the heart." (PMID 34202636, 2021). "Next, we detected the expression of IL-6, IL-1β and TNF-α in RAW264.7 cells after infection with the WT or ΔCRISPR strains." (PMID 34727007, 2021). "Reduced expression of IFN-β and TNF-α in the brain of DCIR−/− mice during the early phase of polioencephalitis (7 dpi) indicates a diminished cytokine response at the infection site." (PMID 34893671, 2021). "The level of TNF-α was increased with infection, and it was significantly higher in control (C1) cells transfected with SifA, IpGB1, IpGB2, and/or MAP compared to ELMO1 (E1) shRNA cells." (PMID 34719317, 2021). "The mRNA levels of Nogo-A, CHOP, IL-6, and TNF-α were also significantly increased after infection with Ad-Nogo relative to the control (Ad-GFP)." (PMID 33572505, 2021). "Under inflammatory conditions, there was an increased activation of IL-1β, IL-6, IL-8, TNF-α in MDCK cells following infection with C. jejuni RC039, S. enterica and C. perfringens." (PMID 34099034, 2021). "In the CF mice, within 48-h of B. pseudohinzii inoculation, there is a significant spike in IL-1β (p = 0.010), IFN-γ (p = 0.032), IL-6 (p = 0.019), and TNF-α (p = 0.040) serum levels, well beyond the infection naïve controls." (PMID 34475490, 2021). "Among serum molecules identified in non-neurological and neurological diseases in the acute phase of the infection, 12 (IL-1β, IL-6, TNF, IL-2, IL-7, IL-17A, IL-15, IFN-α, IL-5, IL-13, IL10, and GM-CSF) were shared by both networks." (PMID 33776990, 2021). "At the same time, they release proinflammatory cytokines and chemokines, such as IL-6, IL-10, IL-1β, MIP-2 and TNF-α, in order to recruit neutrophils at the site of infection." (PMID 33804894, 2021). "Taken together, our results indicated that TNF - TNF receptor 1 signaling is crucial for an appropriated response against N. caninum infection, especially during chronification of the infection in the central nervous system." (PMID 35071042, 2021). "We observed that infection with Mtb aggregates led to a stronger early inflammatory response in human monocyte derived macrophages, with higher secretion of TNFα, as well as upregulation of genes leading to chemotaxis." (PMID 34925266, 2021). "Pan-caspase-inhibition during MVA-infection similarly led to increased TNF and IL-6-secretion, whereas the IFN-I response was induced by additional QVD treatment in Bax/Bak-double-deficient, but not wt cells." (PMID 34711816, 2021). "The IL-10/TNF-α ratio in our study at 12 hpb with infection was 6.6 ± 2.4 and rose to 11.1 ± 3.7 at the onset of symptoms." (PMID 34152806, 2021). "Ahsg was a negative acute-phase reaction protein, mediated by a variety of proinflammatory mediators including TNF-α, thereby reducing the inflammatory response to injury and infection." (PMID 34007409, 2021). "We found significantly more IFNγ and TNF producing CD4+ T cells in brains of infected TKO mice in the chronic stage of infection." (PMID 33968021, 2021). "To probe the role of TNF in epithelial NF-κB signaling during the infection, we generated BMCs by reconstituting p65GFP-FLxTlr4−/− mice with either TNFa+/− or TNFa−/− BM." (PMID 34529751, 2021). "At the initial stage of SARS-CoV-2 or SFTS virus infection, PLT, FIB and TNF-α have definitive clinical value for the early and differential diagnosis of these two infections." (PMID 34238962, 2021).
infection (continued). "PRV GD-WH infection raised the TNF-α transcription level in a time-dependent manner but decreased the transcription of FasL and TraiL." (PMID 34149651, 2021). "In response to infection by L. monocytogenes, trophoblasts produce pro-inflammatory cytokines (predominantly IL-6 and TNFα) as well as neutrophil, natural killer, and monocyte chemokines (predominantly IL8 and MIP-1α/β)." (PMID 34367171, 2021). "Upregulation of TNF-α expression was observed only at 6 h and 24 h post-infection in the S. Typhimurium (21.8-fold) group and S. Gallinarum (4.18-fold) group, respectively." (PMID 34446765, 2021). "The main function of TNF is to stimulate and activate immune cells to the site of infection and to destroy present pathogens like viruses and bacteria." (PMID 33920429, 2021). "Using the multiplex assays, we found that infection of 3-D cervical cell models with M. mulieris significantly upregulated expression of IL-6 (p<0.0001), IL-8 (p<0.0001), MCP-1 (p<0.01) and TNF-α (p<0.01) whereas infection with Eggerthella sp." (PMID 35004344, 2021). "Compatible with the behavior of the MyD88 KO, TLR2 and TLR5 proved important for both IL-6 and TNFα secretion following infection with L. pneumophila." (PMID 34280250, 2021). "The increased levels of TNFα have been reported in secondary heterotypic infection than homotypic, indicating our samples also consist of heterotypic DENV-2 infection." (PMID 34447698, 2021). "These cells respond by releasing inflammatory cytokines such as TNF-α, IL-1β, and IL-6, aiming to eradicate the infection and maintain homeostasis." (PMID 33731173, 2021). "The reduction of c-IAP1 in OTUB1-deficient hepatocytes resulted in diminished apoptosis, induction of necroptosis and ERK-dependent TNF production upon infection with Lm and stimulation with TNF, respectively." (PMID 33712742, 2021). "Similar results were obtained, TNF participated in antimicrobial humoral response-related anti-infection pathways, NCR3 was still involved in natural killer cell mediated immunity." (PMID 34311758, 2021). "S. suis strain P1/7 was able to induce significantly more rapid production and higher levels of IL-6 and TNF-a early in the post-infection period, reaching peaks of 54,027 pg/mL and 2067 pg/mL at 8 h, respectively." (PMID 34357984, 2021). "After infection, TNF-α is abundant and is released in the lung of TB patients, indicating active cytokine stimulation." (PMID 34679707, 2021). "As TNF-α is required for the control of infection and the subsequent immune response, it plays a central role for the host response to infection and injury." (PMID 34696794, 2021). "Our results showed that infection with T. cruzi triggers a robust inflammatory response in the acute phase, with the production of inflammatory cytokines, such as IFNγ and TNFα, which have been shown to activate macrophages to eliminate the parasite." (PMID 34784372, 2021). "In colon organoids, already at 12 hpi hIECs display a strong NFκB and TNF response to infection with this response becoming even more pronounced at 24 hpi (Fig EV5A and B)." (PMID 33904651, 2021). "TNF is mainly produced during the acute phases of the infections and binds to TNF receptor 1 (CD120a, p55, TNFR1) activating a variety of cells, hence playing an important role in the induction of the inflammatory process against diverse pathogens." (PMID 35071042, 2021). "The expression levels of TNF-α after thermal injury and infection were significantly reduced in the hemolymph antibacterial protein treatment group and erythromycin groups." (PMID 34941846, 2021). "TNF-α is a proinflammatory cytokine produced by different cell types, such as macrophages, lymphocytes, and fibroblasts, and reflects inflammation, infection, and other environmental stresses." (PMID 34007291, 2021). "Inflammation is a response against infection, illness and injury by the excessive expressions of chemokines and inflammatory cytokines such as TNF-α, IL-6 and IL-8." (PMID 33646441, 2021).
infection (continued). "On the other hand, MoDCs infection by HSV-2 produced a significant increase in TNF-α and IL-6 expression, with a reduced expression of IFN-β and IL-12p70, and a modest synthesis of IL-10." (PMID 34895058, 2021). "The expression of TNF-α was increased in the spleen and lung after infection with JA1 and SH1 with a fold change of 4.51–10.39, yet decreased in the brain with a fold change of 0.09–0.52." (PMID 33584608, 2021). "The picture that emerges regarding vMIA/vIBO suppression seems reminiscent of adenovirus-encoded viral BCL-2 antagonist E1B 19K, a function that suppresses analogous TNF-mitochondria synergy during infection." (PMID 34578288, 2021). "The capacity of S. parasuis strain BS26 to induce TNF-α production in vivo is obviously lower than that of S. suis strain P1/7 during the whole infection." (PMID 34357984, 2021). "ELISA and qRT-PCR assays indicated that Tat mutant infection significantly induced proinflammatory cytokine (TNF-α and IL-6) and nitric oxide (NO) production." (PMID 34195100, 2021). "To investigate if TNF-α and IL-6 signaling contributes to controlling the infection, we treated infected macrophages with infliximab or tocilizumab and measured the fluorescence intensity of M. avium-DsRed to assess the burden per infected cell." (PMID 34607464, 2021). "This “forces” BM-derived cell types in the mucosa to hyper-produce TNF in an attempt to restrict the infection." (PMID 33731826, 2021). "The relative expression of TNFα and iNOS in the CΔhtpG infection group was significantly lower than that in the WT infection group (p < 0.05)." (PMID 34869065, 2021). "Although immune-suppressive therapies such as anti-TNF agents are effective at ameliorating symptoms in some IBD patients, continued treatment increases susceptibility to infection." (PMID 33767714, 2021). "Next, we measured the expression of proinflammatory cytokines/mediators (IL-1β, TNF-α, IL-6 and iNOS) in brain lysates (cortex and hippocampus) and serum at 24 h post-infection by RT-PCR and ELISA, respectively." (PMID 34727939, 2021). "TNF-α has been shown to be a component of killing/control during O. tsutsugamushi infections, and during infection with other intracellular pathogens, either alone or synergistically with IFNγ or IL2." (PMID 34287349, 2021). "RAW264.7 cells and BMDMs infected with rMS::pMV261-Rv0927c induced a decrease in IL-6, TNF-α, and IL-1β expression, compared with those infected with rMS::pMV261 at 6, 24, and 48 h post-infection." (PMID 34531869, 2021). "The authors described that infection of bone marrow-derived macrophages by L. donovani promastigotes led to secretion of mediators such as TNF-α and GM-CSF by the infected cells, with concomitant inhibition of the release of M-CSF and IL-1β." (PMID 34279684, 2021). "Among the different cytokines and chemokines produced at the initial phase of the inflammatory process, IL-8, and particularly IL-6 and TNF-α have been extensively studied in inflammatory diseases and infections." (PMID 33708198, 2021). "Our results showed that Tat-mutant infection can significantly induce the expression of TNF-α and IL-6." (PMID 34195100, 2021). "Another study also reported an accumulation of a CD103+CD11b+ DC population in the lung, in a mouse model of infection with H. capsulatum treated with an anti-TNF." (PMID 34847189, 2021). "Macrophages are immune sentinels for early recognition of infection and upon pathogen contact they trigger signaling via the release of pro-inflammatory cytokines, such as TNF." (PMID 33717058, 2021). "In order to explicate the difference in mortality between mice infected with S. suis strain P1/7 and S. parasuis strains at early phase of infection, we also compared their kinetics of inducing TNF-a and IL-6 production in vivo within 24 h post-infection." (PMID 34357984, 2021).